HDAC8 (histone deacetylase 8)
Diseases named in the same sentence as HDAC8 in open-access papers (continued):
Sharing a sentence is not in itself a finding about the gene and the disease.
Stroke (1 paper, 2021). Sudden impairment of blood flow to a part of the brain due to occlusion or rupture of an artery to the brain. "Long-term overexpression of HDAC2 and HDAC8 was observed in neurons and astrocytes at 3‒14 days after photothrombotic stroke in the mouse cerebral cortex." (PMID 34680562, 2021). "The expression of HDAC8 in the mouse cortical neurons and astrocytes increased significantly during the recovery period, from 3 to 14 days after photothrombotic stroke." (PMID 34680562, 2021). "The administration of α-phenyltroplon that inhibits both HDAC2 and HDAC8, or MI-192, an inhibitor of HDAC2 and HDAC3, suppressed apoptosis of cortical cells in the penumbra and decreased the infarct volume after photothrombotic stroke in mice." (PMID 34680562, 2021).
X-linked deafness (1 paper, 2024). "First, some X-linked deafness genes were not included in the predefined panel containing 227 HL-related genes, such as RPS6KA3, EFNB1, HDAC8, ARX, and ANOS1, which may cause a negative molecular diagnosis for some patients." (PMID 39272213, 2024).
X-linked intellectual disability syndrome (1 paper, 2016). "A mutation in HDAC8 has also been described in a family with an X-linked intellectual disability syndrome with distinctive facial features, which included hypertelorism." (PMID 27560520, 2016).
cancer (89 papers, 2011 to 2026). A tumor composed of atypical neoplastic, often pleomorphic cells that invade other tissues. "Altogether, these data reinforced our findings that coinhibition of HDAC8 and checkpoint kinases caused synergistic vulnerability during S phase by destabilizing replication forks in cancer cells." (PMID 39436709, 2024). "Dysregulation and overexpression of HDAC8 are implicated in the development of various complex diseases, including cancer and neurodegenerative disorders." (PMID 39611171, 2024). "There is increasing evidence indicating that HDAC8 is upregulated in cancer and associated with tumour cell proliferation, metastasis, immune evasion and drug resistance." (PMID 39317961, 2024). "Dysregulation of HDAC8 has been implicated in the pathogenesis of several diseases, most notably cancer and neurodegenerative disorders." (PMID 39611171, 2024). "Histone deacetylase family member 8 (HDAC8) is implicated in many cancers, and an HDAC8 knockdown system showed decreased cancer progression of human colon, lung, and cervical cells." (PMID 37215636, 2023). "The knockdown of HDAC8 isozyme is associated with the inhibition of cell proliferation and apoptosis enhancement in several cancer cell lines." (PMID 35886887, 2022). "HDAC8 is upregulated in cancer and is associated with tumor cell proliferation, apoptosis, metastasis, immune evasion, and drug resistance." (PMID 36231123, 2022). "To date, HDAC8 activation/inhibition represents a potential tool to counteract X-linked disorders, aberrant wound healing, cancer, and neurological disorders." (PMID 36077415, 2022). "Small molecule CMH (4-(4-chloro-2-methylphenoxy)-N-hydroxybutanamide) was previously shown to downregulate FLIP, rendering cancer cells susceptible to apoptosis via inhibition of the class II deacetylase HDAC-8." (PMID 32630842, 2020). "While all four classes of HDACs have been implicated in various cancers, Class I HDACs (HDAC1, HDAC2, HDAC3, and HDAC8) are generally considered the most directly and frequently associated with tumorigenesis and are often the primary targets in initial cancer therapeutic strategies." (PMID 41440016, 2025). "Notably, cancer cells were more susceptible to HDAC8 inhibition, as both HDAC8 inhibitors induced greater checkpoint activation in MDA-MB-231 cells compared with normal M10 cells." (PMID 39436709, 2024). "Having demonstrated that coinhibition of HDAC8 and checkpoint kinases caused high levels of replication stress, we asked whether cotreatment would be sufficient to trigger cancer cell death." (PMID 39436709, 2024). "HDAC8 has been studied to play a potential role for tumor growth and proliferation, whereas HDAC8 inhibition caused apoptosis, cell death, and cell cycle arrest in various cancer types." (PMID 33980998, 2022). "Consequently, the physiological role of HDAC8 in cells is complex and needs further elucidation but it is clearly linked to relevant cancer mechanisms." (PMID 30292946, 2019). "Indeed, several “cancer-specific” escapees identified here have previously been shown to be involved in cancer, such as HDAC8, which is implicated in cellular transformation and metastasis formation." (PMID 25653311, 2015). "Furthermore, increased HDAC8 activity is known to be associated with several diseases, including neurodegenerative disorders, metabolic deregulation, autoimmune, inflammatory diseases, and cancer." (PMID 37637416, 2023). "More precisely, class I HDACs (HDAC1-3) and HDAC8 play a crucial role in the prevention of apoptosis in BRAF-mutant cancers, including BRAF inhibitor-resistant cells, which can be targeted by isoenzyme-selective inhibitor molecules." (PMID 39935431, 2025).
cancer (continued). "Taken together, these results suggest that arundinin represents a new promising hit as a dual HDAC8/tubulin inhibitor deserving further investigations in advanced preclinical models of human cancer." (PMID 39594568, 2024). "Our investigation has identified arundinin, a polyphenolic compound from traditional Asian medicinal plants, as a potent dual HDAC8/tubulin inhibitor with promising anti-cancer activity." (PMID 39594568, 2024). "HDAC8 plays a significant role in cancer progression, contributing to cancer cell proliferation, metastasis, immune evasion, and drug resistance." (PMID 39611171, 2024). "Overall, the results indicate that radotinib and sertindole can be promising candidates as HDAC8-targeting repurposed drugs against cancer and neuropathological conditions." (PMID 39611171, 2024). "This study identifies a novel function of HDAC8 in guarding the integrity of replicating genome and a cancer-specific synthetic lethality between HDAC8 and checkpoint kinases." (PMID 39436709, 2024). "Functional studies have revealed that HDAC8 plays a pivotal role in the pathogenesis of various cancers, but its involvement in other diseases is less well understood." (PMID 39317961, 2024). "HDAC8 is especially involved in several features of cancer development such as cell division, spreading, immune system avoidance, and chemotherapeutic drug resistance." (PMID 39611171, 2024). "Promising anti-cancer strategies have exploited dual-targeting drugs that inhibit both HDAC8 and tubulin." (PMID 39594568, 2024). "We validated a synergistic vulnerability between HDAC8 and checkpoint kinases that highlights a potentially valuable precision medicine approach to selectively target cancer." (PMID 39436709, 2024). "High expression levels of both HDAC8 and CHK1 or ATR was linked to poor overall survival in a pan-cancer dataset from TCGA." (PMID 39436709, 2024). "Combined treatment with HDAC8 and checkpoint kinase inhibitors leads to synthetic vulnerability in various types of cancer cells." (PMID 39436709, 2024). "Our findings indicate that HDAC8 guards the integrity of the replicating genome, and the cancer-specific synthetic lethality between HDAC8 and checkpoint kinases provides a promising replication stress–targeting strategy for treating a broad range of cancers." (PMID 39436709, 2024). "Synergistic cell killing by dual inhibition of HDAC8 and checkpoint kinase is selective for cancer cells." (PMID 39436709, 2024). "In this context, dual binder small molecules that selectively interact with HDAC8 and tubulin, both involved in the apoptotic process, can be considered an innovative strategy for cancer therapies." (PMID 39594568, 2024). "We showed that simultaneous inhibition of HDAC8 and checkpoint kinases led to extensive replication fork collapse, irreversible cell-cycle arrest, and synergistic vulnerability in various cancer cells." (PMID 39436709, 2024). "Elevated levels of HDAC8 have been reported in many cancers such as breast cancer, neuroblastoma, and acute myeloid leukemia, and these have been associated with shorter survival and more aggressive disease." (PMID 39611171, 2024). "A vast majority of reports have documented the involvement of HDAC8 in tumorigenesis at multifaceted levels to promote cancer cell survival, repress apoptosis, and prevent telomere shortening." (PMID 39436709, 2024). "In cancer, HDAC8 plays a role in cancer development through cell proliferation, metastasis, immune tolerance, and chemoresistance." (PMID 39611171, 2024). "HDAC8 has been demonstrated to be involved in cell cycle regulation in both normal and cancer cells." (PMID 39043961, 2024). "HDAC8 is overexpressed and dysregulated in several types of cancer and neurodegenerative disorders, which calls for potent and selective inhibitors with minimal side effects." (PMID 39611171, 2024).
cancer (continued). "PCI-34051 is one of the most widely used HDAC8-selective inhibitors (HDAC8is), with 200-fold selectivity over other class I HDACs, and it has shown significant anti-cancer effects in various cancer cells." (PMID 36831463, 2023). "Targeting HDAC8 is an attractive target for cancer therapy, and a myriad number of inhibitors have been developed thus far." (PMID 36831463, 2023). "It has been demonstrated that HDAC8 plays a multifunctional role in cancer progression, such as stimulating tumor growth and metastasis by enhancing cell proliferation and activating EMT via acting on histones and non-histone substrates." (PMID 36911746, 2023). "Further studies are required to verify the efficacy of the HDAC8-mediated deacetylation of HIF-1α in other cancer cell lines." (PMID 36831463, 2023). "Another histone deacetylase of class I, the deregulation and overexpression of which are involved in various aspects of the progression of malignant neoplasms, is HDAC8." (PMID 37834214, 2023). "Meanwhile, the multi-target pharmacological approach on HDAC8 has gained attention for its benefits from achieving the simultaneous modulation of multiple targets, especially in complex diseases such as cancer and fibrosis." (PMID 36911746, 2023). "Here, we address the pathological function of HDAC8 in cancer and other diseases, as well as illustrate several HDAC8is that have shown anti-cancer effects." (PMID 36231123, 2022). "Accordingly, genetic ablation or pharmacological inhibition of HDAC8 demonstrates anti-cancer effects in various types of cancer." (PMID 36231123, 2022). "Several reviews elaborated on the beneficial effect deriving from HDAC8 inhibition in a wide range of cancers taking place in blood, breast, liver, colon, lungs, and nervous system." (PMID 36077415, 2022). "In particular, we summarize recent studies of HDAC8 in cancer development and suggest HDAC8 as a potential therapeutic target in human cancers." (PMID 36231123, 2022). "Functional studies of HDAC8 revealed that it plays a pivotal role in the pathogenesis of diseases such as cancer, CdLS, and infectious diseases and raised the need to find selective inhibitors that specifically target HDAC8." (PMID 36231123, 2022). "Overall, the developed PROTACs represent useful tools to investigate the physiological functions of HDAC8 in other cancer cells in future studies." (PMID 35886887, 2022). "A closer look at these factors identified a group of three histone deacetylases (Hdac4, Hdac7, Hdac8) with reported implications in cancer patient's prognosis and with a wide range of available specific inhibitory compounds." (PMID 35016723, 2022). "HDAC8 is especially involved in various aspects of cancer progression, such as cancer cell proliferation, metastasis, immune evasion, and drug resistance." (PMID 36231123, 2022). "Based on our and other studies, specific inhibitors of HDAC8 represent very attractive anti-cancer drugs." (PMID 35016723, 2022). "In this section, we give an overview of the most recent advances relative to HDAC8 engagement in some of the mentioned cancer types clustered in haematological and solid tumours." (PMID 36077415, 2022). "Because α‐tubulin has been newly validated as a substrate for HDAC8 except for HDAC6, the expression and deacetylating tubulin level of HDAC6 differed from HDAC8 in kinds of cancer cells." (PMID 32885602, 2020). "It has been shown that the HDAC8 gene can regulate the biological function of cancer cells both in the cytoplasm and cell nucleus[26 ▶,27 ▶]." (PMID 32429642, 2020). "In order to exclude endogenous interference, we expressed PKM2 wild-type, PKM2-K62R or PKM2-K62Q mutant in HDAC8 knockout cells to analyze its impact on cancer cell metabolism." (PMID 33279948, 2020).
cancer (continued). "In cancer, HDAC8 is either deregulated or overexpressed and reported to interact with transcription factors." (PMID 33096729, 2020). "In recent years, attention has been focused on the targeted inhibition of HDAC8 to control and inhibit the cancer growth[19 ▶]." (PMID 32429642, 2020). "HDAC8 is known to be involved in initiation and progression of different cancers; however, the role of HDAC8 in GBM remains unexplored." (PMID 31798765, 2019). "These immunoblot results are in agreement with human protein atlas data, suggesting differential expression pattern of HDAC6 & HDAC8 in different cancer cell lines, assigning their specific/independent roles in deacetylating their target substrates." (PMID 29716651, 2018). "Overexpression of HDAC8 is clinically observed in some of the adult tissue cancers like colon, breast, lung, pancreas, liver and childhood neuroblastoma." (PMID 29716651, 2018). "Co-IP and reverse-immunoprecipitation results confirmed that HDAC8 and Alpha tubulin do interact not only in cancer cells, HeLa but also in normal HEK 293 T cells." (PMID 29716651, 2018). "HDAC8 is a class I histone deacetylase, which has emerged as an attractive target for drug development in cancer." (PMID 28390197, 2017). "We also noted that “cancer-specific” escapees, such as HDAC8 or NXT2, exhibit additional and/or enlarged H3K4me3 sites in tumor cells when compared to HMEC." (PMID 25653311, 2015). "The work provides support for HDAC8 as a relevant mechanistic target for cancer therapy, beyond its reported involvement in childhood cancer." (PMID 25321483, 2014). "The over expression of HDAC8 was observed in many cancers and thus inhibition of this enzyme has emerged as an efficient cancer therapeutic strategy." (PMID 22272142, 2011). "HDAC8 promotes cancer metastasis by suppressing maspin expression in prostate cancer." (PMID 40260239, 2025). "In addition, recent work has also identified that inhibition of HDAC8 activity can upregulate R-loops in cancer cells." (PMID 40478628, 2025). "Similarly, targeted HDAC8 inhibition sensitizes cancer cells to chemotherapy by suppressing the multidrug resistance gene MDR1." (PMID 40332124, 2025). "We found that simultaneous inhibition of HDAC8 and checkpoint kinases generated substantial levels of DSBs during genome replication and induced an irreversible S-phase arrest, leading to synergistic cytotoxicity specifically in cancer cells." (PMID 39436709, 2024). "Consequently, HDAC8 inhibitors have been tested alone or in combination with other inhibitors in various types of cancer." (PMID 39317961, 2024). "Here, we identify histone deacetylase 8 (HDAC8) as a drug target whose inactivation synergized with the inhibition of checkpoint kinases to elicit substantial replication stress and compromise genome integrity selectively in cancer cells." (PMID 39436709, 2024). "Importantly, coinhibition of checkpoint kinase and HDAC8 induced irreversible early S-phase arrest and triggered apoptosis specifically in cancer cells." (PMID 39436709, 2024). "Previous studies have heavily focused on the role of HDAC8 in cancer progression." (PMID 39317961, 2024). "In cancer, HDAC8 has been shown to promote growth, metastasis, and immune evasion; consistently, its genetic ablation or pharmacological inhibition elicited anti-cancer effects across various cancer types." (PMID 39594568, 2024). "Collectively, these data suggest that HDAC8 may functionally interact with key regulators in genome maintenance pathways to sustain chromatin replication in cancer cells." (PMID 39436709, 2024). "Given that HDAC8 is upregulated in many cancer tissues, HDAC8 inhibitors could be considered as top candidate agents to enhance the efficacy and safety of checkpoint kinase inhibitors in cancer therapeutics." (PMID 39436709, 2024).